AURKB (aurora kinase B)
Diseases named in the same sentence as AURKB in open-access papers (continued):
Sharing a sentence is not in itself a finding about the gene and the disease.
cancer (continued). "Survivin, an IAP family member and substrate of PLK1 and AURKB, is involved in carcinogenesis, tumor progression, cancer cell proliferation, inhibition of apoptosis, neoangiogenesis, and drug resistance." (PMID 36627281, 2023). "The inhibitor downregulates the Aurora B kinase (AURKB) expression, which is involved in mitosis and a therapeutic target in cancers." (PMID 37834411, 2023). "Of the epigenetic signatures that were modified due to HCV fitness, AURKB and H4K20Me3 are especially noteworthy for their implication in cancer." (PMID 36992689, 2023). "Overall, we found that LXY18 was more potent than AURKB kinase inhibitors in a panel of human cancer cell lines, despite appearing to work, at least in part, through CPP complex mislocalization." (PMID 37903144, 2023). "Integrated bioinformatic analysis of The Cancer Genome Atlas and immunohistochemistry staining of patients' tissues revealed the oncogenic role of aurora kinase B (AURKB) in UM." (PMID 37079315, 2023). "AURKB is a central regulator of chromosome separation and cytokinesis and is abnormally expressed in various cancer cells." (PMID 37318676, 2023). "Studies have shown that AURKB inhibited the intrinsic resistance of malignant tumors to autophagy-related death by overcoming Bcl-2 expression." (PMID 36561847, 2022). "AURKB promotes survival of cancer cells by cell cycle progression with phosphorylating a series of downstream substrates, including RacGAP1." (PMID 35222021, 2022). "To investigate the importance of AURKB and TβRI for cancer progression, we next determined their activity, expression, and complex formation in clinically derived samples." (PMID 35853811, 2022). "When combining the top 100 co-expressed genes for each cancer type, some genes occurred more than once, e.g. AURKB (encoding for Aurora kinase B) and CDC20 (encoding for Cell division cycle 20) were the most frequent among the combined list of 3200 genes." (PMID 35331169, 2022). "In this way a combined inhibition of EGFR and AURKB not only efficiently eliminates cancer cells but also overcomes resistance beyond EMT." (PMID 36387232, 2022). "AURKB expression has been shown to positively regulate cancer proliferation, metastasis, and drug resistance." (PMID 36561847, 2022). "AURKB, an established oncogene, is overexpressed in many cancers including PCa, which drives tumorigenesis via cell proliferation, cell cycle progression and cell survival." (PMID 35612714, 2022). "Our data shows that TRAF6-induced K63-linked polyubiquitination on K85 and K87 in the beginning of kinase domain of AURKB occurs during mitotic progression of cancer cells when AURKB is active." (PMID 35853811, 2022). "A group of small-molecule inhibitors of AURKB, with ongoing or completed Phase I and II trials, have recently been proposed as potential drugs for cancer treatment." (PMID 36529823, 2022). "Many studies have confirmed that AURKB is a crucial carcinogenic factor in different kinds of carcinoma." (PMID 35354488, 2022). "This review summarizes recent findings pertaining to the role of AURKB in tumor development, therapy related drug resistance, and its inhibition as a potential therapeutic strategy for cancer." (PMID 33915740, 2021). "Although the only inhibitor in clinical trials, CFI-400945 exhibits considerable antiproliferative actions in cancer, it also has activity against AURKB, TRKA, TRKB, and Tie2/TEK." (PMID 33777739, 2021). "Several clinical studies are ongoing with the therapeutic aim of inhibiting AURKB in an effort to target genes involved in the “BIRC5 cancer network” and clinical responses indicate a central role of this pathway in proliferating leukaemic cells." (PMID 34638823, 2021). "Further, several of the AURKB inhibitors have off-target effects on other kinases; and therefore, we need to develop and test more specific AURKB inhibitors for future use in fight against cancer." (PMID 33915740, 2021).
cancer (continued). "Previous evidence also reveals the importance of targeting AURKB/AURKA in cancer cells with activated YAP." (PMID 33805359, 2021). "The methylation of Arg887 in INCENP facilitates its interaction with AURKB, thereby augmenting AURKB activity and contributing to the enhancement of chromosome alignment and segregation during mitosis in cancer cells." (PMID 34006904, 2021). "The regenerative capacity of motor axons has also been perturbed after inhibition of Aurora kinase B (AurkB), a serine/threonine kinase mostly studied in different types of human cancers." (PMID 33801205, 2021). "In turn, nuclear HSP70 promotes aurora kinase B (AURKB) activity, which is normally dysregulated in cancer cell lines." (PMID 33445445, 2021). "AURKA and AURKB have been found to function as oncogenes to promote tumorigenesis in multiple types of cancer including solid tumors and hematological malignancies." (PMID 33451333, 2021). "AURKB promotes cancer growth and invasion and, therefore, was found to be a promising target for cancer treatment." (PMID 34003798, 2021). "Even though, AURKA has attracted researchers’ attentions and has been a more popular target than AURKB for cancer therapy with nearly fifty clinical trials using specific AKIs." (PMID 33451333, 2021). "AURKA and AURKB also consistently scored high across every cancer cohort, as did other cell-cycle- and mitoses-related kinases (BUB1B, BUB1, CDK1)." (PMID 33205077, 2020). "Numerous studies have found that the overexpression of AURKB exists in a variety of cancer cell lines." (PMID 32626756, 2020). "AURKB, which is highly characterised within the context of cancer cell division, played a vital role in SG functional restoration and structural re-population, post transient innate immune-mediated injury and acinar depletion." (PMID 31383943, 2019). "This further supports the observed antagonistic effect of CSF1R and AURKB, where the inhibition of both rescued the cancer cells." (PMID 31312514, 2019). "In all cases, motility was only blocked by co-inhibition of PLK4 and AURKB/C, indicating these kinases are functionally redundant in a variety of cancer contexts." (PMID 31142743, 2019). "Of note, Aurora kinase B, one of the essential kinases for cell division via regulating mitosis, is also upregulated in multiple cancer types, and its overexpression leads to unequal distributions of genetic information and, subsequently, aneuploidy." (PMID 30918060, 2019). "In particular, dimethylation of K561 of HSP70 by SETD1A regulates the subcellular localisation of this protein and it promotes the proliferation of cancer cells through its interaction with Aurora Kinase B (AURKB)." (PMID 30050697, 2018). "In corroboration with aberrant elevation of RecQL4 in human cancers, abnormal activation of AURKB was also observed to be a frequent event in human cancer cells." (PMID 30206236, 2018). "Our observation have revealed that miR-SX4 downregulated the expression of several cancer cell survival proteins such as AurkB and Survivin39,49,50, and hence there is a potential of miR-SX4 to induce necrosis in cancer cells." (PMID 29343703, 2018). "For the first time, the functional interaction of AURKA and AURKB has been found, which aids in the protection of their stability, and partially explains their constant high expression and activity in cancers." (PMID 28595628, 2017). "The most attractive inhibitors are those that target cell cyclin dependent kinases (e.g. CDK1) and aurora kinases (e.g. AURKA, AURKB), which are abundantly expressed in various cancer types." (PMID 28183295, 2017).
cancer (continued). "It has been reported that disruption expression or kinase activity of AURKA or AURKB in cancer cells impairs mitotic progression and results in G2/M phase arrest." (PMID 28595628, 2017). "The ectopic expression of AURKA and AURKB is closely correlated with carcinogenesis, the epithelial-to-mesenchymal transition, cancer cell stemness, and drug resistance." (PMID 28595628, 2017). "AURKA and AURKB are also overexpressed in a variety of human cancers, and the activation of AURKA and AURKB has oncogenic effects." (PMID 27636990, 2016). "Several molecular components, for example, Aurora kinase B, kinesin-13 proteins, MCAK, INCENP, Survivin, and Shugoshin are associated in this phenomenon and their overexpression are reported in cancers of various origins." (PMID 25999914, 2015). "Knockdown of PRMT1 as well as overexpression of methylation-inactive INCENP attenuated the AURKB activity in cancer cells, and resulted in abnormal chromosomal alignment and segregation." (PMID 26460953, 2015). "Over expression of Aurora kinase B is evident in a range of primary cancers, such as prostate, head and neck, colon and thyroid cancers, and is associated with clinical aggressiveness." (PMID 25885472, 2015). "Subsequently, dysregulation of AURKB was reported in various types of solid tumor, and clinical trials of anti-cancer drugs targeting AURKB have been actively conducted." (PMID 26460953, 2015). "A report states that enhanced lysine methylation of HSP70 promoted proliferation of cancer cells through activation of a kinase enzyme named aurora kinase B." (PMID 25610655, 2014). "In other tissues such as the thyroid gland, brain and colon AURKB was found to be overexpressed in cancers compared to normal tissues." (PMID 20411023, 2010). "Given that MOF-mediated acetylation of AURKB at K215 is implicated in early mitosis, we hypothesized that MOF may regulate cancer cell proliferation through AURKB." (PMID 40710353, 2025). "Dysregulated AURKB is believed to confer a proliferative advantage to cancer cells." (PMID 40710353, 2025). "Of these, key cancer-associated genes shown to be upregulated by the SySa fusion were downregulated by TAK-981 treatment, including CDX2, HOXA10, SUZ12, TYMS, AURKB, and HOXC10 and SMC2." (PMID 40804185, 2025). "Based on these findings, it has been suggested that the let-7b-5p/AURKB axis may affect cancer processes by influencing several key genes." (PMID 39787178, 2025). "The AURKB gene is overexpressed in many cancer types including BC." (PMID 39787178, 2025). "The AURKB/CDCA8 pathway is potentially pivotal in cancer pathogenesis." (PMID 39787178, 2025). "Although the role of AURKB as a cancer‐promoting gene has been widely studied, its role in regulating therapeutic resistance remains largely unknown." (PMID 40099930, 2025). "Whether MOF directly acetylates AURKB, and how this modification affects AURKB stability and cancer progression, remains unknown." (PMID 40710353, 2025). "Most importantly, we found that AURKB is significantly associated with immune cell infiltration, immune factors, immune checkpoints, TMB and MSI, which can effectively predict the response to cancer immunotherapy." (PMID 38898693, 2024). "CCNA2, TTK, TOP2A, AURKA, AURKB and BUB1B are also closely associated with cancer." (PMID 39537209, 2024). "Moreover, the AURKB gene has been validated as an actively involved oncogene in cancer and displays a significant inverse correlation with cancer prognosis." (PMID 38898693, 2024). "This study, therefore, seeks to elucidate the multifaceted role of AURKB in diverse cancer types." (PMID 38898693, 2024). "This research marks the first investigation into the correlation between AURKB and pan‐cancer." (PMID 38898693, 2024).
cancer (continued). "Furthermore, the study examined variations in AURKB expression among 18 cancer‐paired samples obtained from the TCGA dataset." (PMID 38898693, 2024). "We speculate that the temporal juncture between 5-FU induced replication stress and AURKB inhibition, which induces endoreplication, promotes cancer cell death." (PMID 38287178, 2024). "AURKB is oncogenic and plays a key role in aneuploidy formation and cancer progression." (PMID 38396874, 2024). "Because it has been suggested that overexpression of AURKA and AURKB is related to a more aggressive type of cancer such as TNBC, identifying molecules that could target the AURKs is a promising step toward developing novel therapies." (PMID 38886738, 2024). "The use of inhibitors that simultaneously target AURKB is a promising cancer treatment strategy." (PMID 38396874, 2024). "Furthermore, we examined the correlation between AURKB expression levels, immune cell infiltration in pan‐cancer tissues, immune‐related gene expression, as well as tumour mutational burden (TMB) and microsatellite instability (MSI)." (PMID 38898693, 2024). "Nevertheless, the role of AURKB in human cancer biology is largely unclarified." (PMID 38713155, 2024). "The strengths of our study are the exploration of the high level of expression of AURKB genes and proteins in cancer and the correlation with poor prognosis, as well as the role of AURKB in the immune pathway, in particular its potential application in cancer immunotherapy." (PMID 38898693, 2024). "The results showed that AURKB was highly expressed in pan-cancer." (PMID 38515112, 2024). "AKT was reported to phosphorylate AURKB on threonine 73, which protected it from proteasome degradation in cancer cells, and in PI3K/PTEN pathway altered tumor cell lines that lack a co-existence of KRAS-BRAF mutation are highly addicted to AKT maintenance of AURKB." (PMID 38233848, 2024). "Notably, AURKB expression was positively correlated with CD4+ Th (T‐helper) 2 cells in all cancers except TGCT." (PMID 38898693, 2024). "AZD1152 was proved to be a specific inhibitor for AURKB with anti-cancer effects." (PMID 38713155, 2024). "The TIMER 2.0 database was used to assess the expression level of AURKB in pan-cancer." (PMID 38515112, 2024). "Elevated levels of AURKB were detected in the advanced stages of 10 different cancers." (PMID 38898693, 2024). "Alternatively, the increased sensitivity of cancer cells to LXY18 could be attributed to the inhibition of an upstream regulator of AURKB which has additional roles to play in mitosis, aside from regulating AURKB localization." (PMID 37903144, 2023). "This new activity suggests that the compound may be a promising drug candidate for cancer treatment and that it can also be used as a tool compound to further dissect the regulatory network controlling AURKB localization." (PMID 37903144, 2023). "The results showed that AURKB expression was higher in cancer specimens than in normal eyes." (PMID 37079315, 2023). "Moreover, AURKB expression has been identified as a prognostic marker in several cancers, including oral cancer." (PMID 36982384, 2023). "In our case, GSK1070916 inhibits AURKB promoting apoptosis of the cancer cell." (PMID 37432499, 2023). "Intriguingly, Kyoto Encyclopedia of Genes and Genomes functional pathway analysis of TCGA revealed that telomere gene sets, widely accepted for their roles in cancer initiation and metastasis regulation, very likely participated in oncogenesis and the progression of UM under the control of AURKB." (PMID 37079315, 2023). "AURKB has, therefore, been investigated extensively as a drug target for cancer therapy." (PMID 37903144, 2023). "Therefore, drugs targeting AURKB have become increasingly significant in recent years due to their potential to disrupt mitotic control of cancer cells while triggering a lethal cell death due to mitotic failure namely mitotic catastrophe." (PMID 36982384, 2023).
cancer (continued). "We finally performed Kyoto Encyclopedia of Genes and Genomes pathway analysis in TCGA and revealed that genes compromising telomere program signature, widely accepted for its role in cancer initiation and metastasis, were highly enriched in UM samples with higher AURKB level." (PMID 37079315, 2023). "Cancer cells could gain an advantage by modifying AURKB in a manner similar to how it functions during mitosis." (PMID 36982384, 2023). "Similar to the function of AURKB in mitosis, it is expected that the changes of AURKB amplification or overexpression could promote the proliferation of cancer cells." (PMID 37318676, 2023). "AURKB has also been reported as a factor related to chemotherapy resistance in other cancers." (PMID 34593983, 2023). "Taken together, the findings presented in this study demonstrate a previously unknown function of TβRI in regulating cancer cell proliferation, i.e., through interaction with AURKB when the cells enter mitosis." (PMID 35853811, 2022). "Aurora kinase B and cSrc are involved in various cancers and other human diseases." (PMID 36139387, 2022). "In recent decades, AURKB has become a hot spot in cancer research." (PMID 35088239, 2022). "The role of the AURKB expression in cancer prognosis is controversial." (PMID 36199443, 2022). "Moreover, eleven kinases were cancer-associated, some of which include FYN proto-oncogene tyrosine kinase (FYN), aurora kinase B (AURKB), and integrin-linked kinase (ILK)." (PMID 33499132, 2021). "To verify this hypothesis, we relied on cancer studies, which comprehensively characterise the array of damage signals downstream of AURKB inhibition." (PMID 33462217, 2021). "Targeting both AURKA and AURKB in tumors of these cancer types may exert considerable antitumor effects." (PMID 33451333, 2021). "Thus, using targeted agents for DDR pathways, including inhibitors of ATR/CHK1, PARP, ATM, cyclin-dependent kinase 4/6 (CDK4/6), DNA-PK, WEE1, and aurora kinase B (AURKB) opens new exciting avenues for clinical development of ICB for cancer treatment." (PMID 34930377, 2021). "Additionally, we have retrieved expression data of AURKB from Gene Expression Profiling Interactive Analysis (GEPIA) database for a variety of cancers and compared it to their respective normal tissue counterparts." (PMID 33915740, 2021). "Results from these studies showed a functional relationship between AURKB inhibition and excessive generation of reactive oxygen species (ROS) in therapeutic modalities of cancer, as a mechanism of cytotoxicity induced by the aurora kinase inhibitor, Barasertib29." (PMID 33462217, 2021). "Drawing parallels with the functions of AURKB in mitosis, it is anticipated that alterations of AURKB either as amplification or overexpression could provide a proliferative advantage to cancer cells." (PMID 33915740, 2021). "The expression of AURKA and AURKB during the G2/M phase transition is tightly coordinated with histone H3 phosphorylation while the overexpression of both kinases is observed in a variety of human cancers." (PMID 32138169, 2020). "For example, cancer cells adapt to decreased microtubule-kinetochore dynamics and suppressed CIN induced by treatment with KIF2C/MCAK inhibitors by adjusting AURKB levels, ultimately returning the cancer cells to their original level microtubule-kinetochore dynamics and chromosome mis-segregation." (PMID 33066048, 2020). "AURKB is overexpressed in a wide range of cancer types 26-28." (PMID 32863956, 2020). "However, AURKB RNA levels in vehicle-treated cells increased only 1.2 fold in mitosis, consistent with dysregulated expression in these cancer cells." (PMID 32539694, 2020). "With the discovery of abnormal expression of AURKB in cancer cells, researchers realized that it may become a new target for cancer treatments." (PMID 32626756, 2020).